PCDHA9 (protocadherin alpha 9)
Description:
Potential calcium-dependent cell-adhesion protein. May be involved in the establishment and maintenance of specific neuronal connections in the brain.
Synonyms: KIAA0345; PCDH-ALPHA9
Tractability: Antibody: UniProt places it where antibodies can reach, with medium confidence; UniProt predicts a signal peptide or a membrane-spanning region; its Gene Ontology location is reachable by antibodies, with medium confidence.
Gene: Protein-coding gene on chromosome 5 (140,847,772 to 141,012,347, forward strand). Ensembl gene ENSG00000204961.
Subcellular location: Cell membrane
Gene Ontology:
Molecular function: cell adhesion molecule binding; calcium ion binding
Biological process: cell adhesion; homophilic cell-cell adhesion; nervous system development
Cellular component: plasma membrane; membrane
Genetic constraint (gnomAD): Loss-of-function variants: 60 observed, 60.53 expected, observed/expected ratio (o/e) 0.99, 90% interval 0.8 to 1.23. The upper end of that interval is the gene's LOEUF score, 1.23, which puts it in group 5 of 6, group 1 being the genes least tolerant of losing a copy. Missense variants: 1,149 observed, 1,165.2 expected, observed/expected ratio (o/e) 0.99, 90% interval 0.94 to 1.03. Synonymous variants: 532 observed, 525.94 expected, observed/expected ratio (o/e) 1.01, 90% interval 0.94 to 1.09.
Homologues: Orthologues: mouse Pcdha8 (84% identical), mouse Pcdha7 (81% identical). Paralogues in human: PCDHA7 (89% identical), PCDHA4 (84% identical), PCDHA3 (83% identical), PCDHA13 (81% identical), PCDHA10 (81% identical), PCDHA1 (80% identical), PCDHA8 (80% identical), PCDHA6 (80% identical), PCDHA2 (80% identical), PCDHA5 (80% identical), PCDHA12 (79% identical), PCDHA11 (79% identical), and 49 more.
Diseases named in the same sentence as PCDHA9 in open-access papers:
PCDHA9 is named in the same sentence as 7 diseases in open-access papers, as found by Europe PMC text mining. Sharing a sentence is not in itself a finding about the gene and the disease. The quoted sentences say what the papers report.
Hirschsprung disease (2 papers, 2023 to 2024). Hirschsprung disease (HSCR) is a congenital intestinal motility disorder that is characterized by signs of intestinal obstruction due to the presence of an aganglionic segment of variable extent in the terminal part of the colon. "Nevertheless, there is little definitive evidence for a causal relationship between PCDH-α and diseases, although a PCDHA9 variant was detected in human Hirschsprung’s disease and a mutation in Pcdhα9 was shown to contribute to CHD in mice." (PMID 38467605, 2024). "PCDHA9 has been identified as a potential candidate gene for Hirschsprung’s disease." (PMID 37627046, 2023).
hypoplastic left heart syndrome (2 papers, 2017 to 2018). Hypoplastic left heart syndrome (HLHS) refers to the abnormal development of the left-sided cardiac structures, resulting in obstruction to blood flow from the left ventricular outflow tract. "Forward genetics in mice was used recently to identify an interaction between two genes, Sap130 and Pcdha9, in causing hypoplastic left heart syndrome (HLHS)." (PMID 30355621, 2018).
breast carcinoma (1 paper, 2022). "As an example of TET2 CD–mediated gene activation, a subset of TSS-CGIs from the breast cancer-methylated PDCHA locus selectively gained H3K4me3 in TET2 CD cells in correlation with the activation of the associated genes as shown for PCDHA4, PCDHA3, PCDHA9, and PCDHA10." (PMID 35351824, 2022).
PCDHA9 also shares sentences with these, for which no sentence is quoted: amyotrophic lateral sclerosis (1 paper); heart disease (1); septal defects (1); ventricular septal defect (1).